CDKN2A (cyclin dependent kinase inhibitor 2A)
Description:
Capable of inducing cell cycle arrest in G1 and G2 phases. Acts as a tumor suppressor. Binds to MDM2 and blocks its nucleocytoplasmic shuttling by sequestering it in the nucleolus. Binds to BCL6 and down-regulates BCL6-induced transcriptional repression. Binds to E2F1 and MYC and blocks their transcriptional activator activity but has no effect on MYC transcriptional repression. Binds to TOP1/TOPOI and stimulates its activity. This complex binds to rRNA gene promoters and may play a role in rRNA transcription and/or maturation. Interacts with NPM1/B23 and promotes its polyubiquitination and degradation, thus inhibiting rRNA processing. Plays a role in inhibiting ribosome biogenesis, perhaps by binding to the nucleolar localization sequence of transcription termination factor TTF1, and thereby preventing nucleolar localization of TTF1 (By similarity). Interacts with COMMD1 and promotes its 'Lys63'-linked polyubiquitination. Interacts with UBE2I/UBC9 and enhances sumoylation of a number of its binding partners including MDM2 and E2F1. Binds to HUWE1 and represses its ubiquitin ligase activity. May play a role in controlling cell proliferation and apoptosis during mammary gland development. [Isoform smARF]: May be involved in regulation of autophagy and caspase-independent cell death; the short-lived mitochondrial isoform is stabilized by C1QBP. Acts as a negative regulator of the proliferation of normal cells by interacting strongly with CDK4 and CDK6. This inhibits their ability to interact with cyclins D and to phosphorylate the retinoblastoma protein.
Synonyms: CDK4I; MTS-1; p16INK4A; CDKN2; MTS1; ARF; MLM; p16; INK4a; CMM2; p19; p14; INK4; p19Arf; p14ARF; P16-INK4A; CAI2; P16INK4; TP16
Tractability: No criterion of Open Targets' tractability assessment is met for any kind of drug.
Gene: Protein-coding gene on chromosome 9 (21,967,752 to 21,995,301, reverse strand). Ensembl gene ENSG00000147889.
Subcellular location: Cytoplasm; Nucleus; Nucleus, nucleolus; Nucleus, nucleoplasm; Mitochondrion (Isoform smARF)
Subcellular location (Human Protein Atlas): Nucleoplasm; Cytosol; Primary cilium; Primary cilium tip; Primary cilium transition zone
Pathways (Reactome):
Disease: Defective Intrinsic Pathway for Apoptosis Due to p14ARF Loss of Function; Evasion of Oncogene Induced Senescence Due to Defective p16INK4A binding to CDK4; Evasion of Oncogene Induced Senescence Due to Defective p16INK4A binding to CDK4 and CDK6; Evasion of Oncogene Induced Senescence Due to p14ARF Defects; Evasion of Oxidative Stress Induced Senescence Due to Defective p16INK4A binding to CDK4; Evasion of Oxidative Stress Induced Senescence Due to Defective p16INK4A binding to CDK4 and CDK6; Evasion of Oxidative Stress Induced Senescence Due to p14ARF Defects
Cellular responses to stimuli: Nuclear events mediated by NFE2L2; Oncogene Induced Senescence; Oxidative Stress Induced Senescence; Senescence-Associated Secretory Phenotype (SASP)
Gene expression (Transcription): RUNX3 regulates p14-ARF; Regulation of RUNX3 expression and activity; Transcriptional Regulation by VENTX
Cell Cycle: Cyclin D associated events in G1
Metabolism of proteins: SUMOylation of DNA damage response and repair proteins; SUMOylation of transcription factors
Developmental Biology: Regulation of MITF-M-dependent genes involved in cell cycle and proliferation
Programmed Cell Death: Apoptotic factor-mediated response
Gene Ontology:
Molecular function: cyclin-dependent protein serine/threonine kinase inhibitor activity; NF-kappaB binding; protein binding; protein kinase binding; RNA binding
Biological process: cellular senescence; negative regulation of cell growth; negative regulation of cell population proliferation; negative regulation of cell-matrix adhesion; negative regulation of cyclin-dependent protein serine/threonine kinase activity; negative regulation of DNA-templated transcription; negative regulation of transcription by RNA polymerase II; Ras protein signal transduction; regulation of cell cycle; regulation of G1/S transition of mitotic cell cycle; replicative senescence; positive regulation of macrophage apoptotic process; positive regulation of smooth muscle cell apoptotic process
Cellular component: cytoplasm; nucleoplasm; nucleus; senescence-associated heterochromatin focus; cytosol
Genetic constraint (gnomAD): Loss-of-function variants: 3 observed, 9.8 expected, observed/expected ratio (o/e) 0.31, 90% interval 0.14 to 0.79. That is too few expected variants to judge how well the gene tolerates losing a copy. Missense variants: 265 observed, 211.93 expected, observed/expected ratio (o/e) 1.25, 90% interval 1.13 to 1.38. Synonymous variants: 122 observed, 99.8 expected, observed/expected ratio (o/e) 1.22, 90% interval 1.05 to 1.42.
Gene-disease validity (ClinGen):
ClinGen rates the evidence that CDKN2A causes each of these diseases.
melanoma-pancreatic cancer syndrome (autosomal dominant): Definitive.
Cancer hallmarks: angiogenesis (suppresses); suppression of growth (promotes); escaping programmed cell death (suppresses); invasion and metastasis (suppresses)
Homologues: Orthologues: pig CDKN2A (81% identical), guinea pig CDKN2A (69% identical), mouse Cdkn2a (62% identical), rat Cdkn2a (51% identical), tropical clawed frog cdkn2b (40% identical). Paralogues in human: CDKN2B (69% identical).
Diseases named in the same sentence as CDKN2A in open-access papers:
CDKN2A is named in the same sentence as 779 diseases in open-access papers, as found by Europe PMC text mining. Sharing a sentence is not in itself a finding about the gene and the disease. The quoted sentences say what the papers report.
melanoma (930 papers, 1999 to 2026). A malignant, usually aggressive tumor composed of atypical, neoplastic melanocytes. "Conversely, complete loss of p16 is strongly associated with homozygous CDKN2A deletion, a hallmark of melanoma progression." (PMID 41596618, 2026). "Functionally, loss of the CDKN2A protein product, p16INK4a, promoted metastatic dissemination of human melanoma cells in a mouse model." (PMID 41596618, 2026). "Variants in CDKN2A account for up to 40% of melanoma-prone families, with an additional ~10% explained by other genes." (PMID 42183343, 2026). "Using a CRISPR-Cas9-engineered model of melanoma initiation, the authors identified a direct signaling pathway where loss of CDKN2A leads to the activation of E2F1, which upregulates the lineage-restricted transcription factor BRN2." (PMID 41596618, 2026). "PGVs in CDKN2A that affect only the tumor-suppressor protein p16(INK) confer increased risk for melanoma and PC." (PMID 39932614, 2025). "To evaluate the therapeutic efficacy of CD38i, we subcutaneously engrafted the YUMM1.7 mouse melanoma tumor, which carries human-relevant mutations (BrafV600E; Cdkn2a−/−; Pten−/−; Tyrosinase:CreERT2), in B6 mice." (PMID 40117361, 2025). "It has been shown that melanoma tumors with loss of CDKN2A are often highly sensitive to CDK4/6 inhibition." (PMID 40904502, 2025). "For CDKN2A, a gene known for an increased risk of pancreatic cancer and melanoma, we found only a second-degree relative with pancreatic cancer." (PMID 39815370, 2025). "The CDKN2A mutation occurs in approximately 20%–40% of high‐risk families, accounting for 1%–2% of melanomas overall, a condition known as the familial melanoma syndrome (FMS)." (PMID 39420514, 2025). "All members of families with combined occurrence of pancreatic cancer and melanoma should be counseled and offered screening for CDKN2A mutations to identify high‐risk family members who should be enrolled in a clinical screening program." (PMID 39609109, 2025). "Mutations in the CDKN2A gene present the most prevalent genetic cause of increased susceptibility to the development of both melanoma and pancreatic cancer." (PMID 39609109, 2025). "CDKN2A was the first, and mostly commonly mutated, familial melanoma predisposition gene identified." (PMID 39420514, 2025). "Germline CDKN2A variants are identified in 20–40% of familial melanoma cases, with mutation penetrance varying widely (5–70%) across populations." (PMID 39941357, 2025). "(CDKN2A did reach exome-wide significance for association with melanoma in this dataset using a Wald test, but this is likely to have been exaggerated, as the likelihood ratio p value was 0.00041)." (PMID 40073867, 2025). "Until recently, the primary genes that were recognized and clinically evaluated for predisposition to melanoma were CDKN2A/ARF (cyclin-dependent kinase inhibitor 2A) and its associated gene CDK4 (cyclin-dependent kinase 4)." (PMID 40558591, 2025). "In the majority of cases where inherited melanoma susceptibility variants are detected, the variants are linked to the CDKN2A gene." (PMID 40072281, 2025). "Within the highly penetrant genes, the most commonly associated to hereditary susceptibility to melanoma is the CDKN2A gene." (PMID 40869905, 2025). "CDKN2A is a key gene in the cell cycle which was initially associated with melanoma-prone individuals." (PMID 41463216, 2025). "Germline mutations in CDKN2A have also been associated with an increased risk for pancreatic cancer which can co-occur in a subset of melanoma-prone families." (PMID 40282469, 2025). "Another crucial factor in melanoma progression is the mutation of the CDKN2A gene, which encodes the tumour suppressor protein p16." (PMID 41155720, 2025). "The main germline molecular alterations related to the risk of developing melanoma are alterations in the CDKN2a, CDK4, MC1R, BAP1, TERT, MITF, PTEN genes." (PMID 40614549, 2025).
melanoma (continued). "Non-CDKN2A variants, relative penetrance in low-melanoma-incidence countries, other tumor associations, and recommended screening." (PMID 40558591, 2025). "Nevertheless, also considering that penetrance varies depending on other environmental and genetic factors, CDKN2A mutations are usually related to early age of melanoma onset, multiple primary melanomas, and a high number of affected family members." (PMID 40869905, 2025). "For example, approximately 40% of melanoma-prone families possess inactivating germline mutations in CDKN2A, which encodes p16INK4A." (PMID 40282469, 2025). "Patients with germline CDKN2A mutations tend to develop multiple primary melanomas (p < 0.001) and present, on average, 15 years earlier than those with sporadic disease (p < 0.001)." (PMID 40981345, 2025). "First, genetic variants of the melanocortin-1 receptor (MC1R), which affect pigmentation traits, significantly increase melanoma risk, both independently of skin phototype and in combination with other risk alleles (e.g., CDKN2A mutations)." (PMID 41011113, 2025). "Germline mutations in CDKN2A gene can be responsible for the development of a syndrome characterized by multiple clinically atypical nevi, melanomas and, in a subset of patients, pancreatic cancer." (PMID 39609109, 2025). "Genetic mutation, especially in the BRAF, NRAS, and CDKN2A genes, plays a very significant part in the development of melanoma." (PMID 41049012, 2025). "Owning to the common embryologic precursor of the neuroectoderm, some germline CDKN2A mutations are prone to develop both melanomas and neural system tumors." (PMID 40046620, 2025). "Genetic predisposition is significant as 5–12% of melanoma cases are familial and often linked to high-penetrance mutations in genes such as CDKN2A, BAP1, and MC1R involved in DNA repair, immune function, cell adhesion, transcription, and melanin production." (PMID 41283485, 2025). "CDKN2A molecular screening is recommended to assess the presence of a melanoma predisposing-syndrome." (PMID 40869905, 2025). "Patients with germline mutations in the tumor suppressor gene CDKN2A are at an increased risk of developing melanoma at some point in their lifetime." (PMID 40687210, 2025). "The occurrence of MPMs and their anatomical distribution among heritable Rb survivors mirrors patterns observed in melanoma-prone families carrying CDKN2A or CDK4 mutations, further supporting potential shared genetic susceptibilities." (PMID 41234990, 2025). "CDK4 activation inhibits the retinoblastoma protein, promoting cell cycle progression, and is usually associated with tumor suppressor CDKN2A (p16INK4A) deletion, furthering melanoma cell survival." (PMID 40076927, 2025). "Germline pathogenic variants in CDKN2A are well established as an underlying cause of familial malignant melanoma." (PMID 40072281, 2025). "In BRAF-mutant melanomas, loss of the CDKN2A gene is typical, but amplification of MITF and CD274 (coding for PD-L1; programmed death ligand 1) is relatively common." (PMID 40361349, 2025). "For instance, mutations in the CDKN2A gene, commonly observed in Caucasian melanoma patients, are rare in East Asia." (PMID 40371294, 2025). "The clinical phenotype observed in families with CDK4 variants is similar to that of families with CDKN2A variants, exhibiting a significant presence of dysplastic nevi, along with an elevated risk of developing multiple primary melanomas." (PMID 40558591, 2025). "The CDKN2A mutation is frequently seen in familial melanoma syndromes, although somatic CDKN2A mutations can also be found in sporadic melanomas." (PMID 40331942, 2025).
melanoma (continued). "The cyclin-dependent kinase inhibitor 2A (CDKN2A) gene is the most commonly mutated gene in familial melanoma; however, CDKN2A mutations explain up to 40% of hereditary cases." (PMID 40869905, 2025). "CDKN2A mutation inactivation has been reported to be associated with melanoma, NSCLC, head and neck cancers, prostate, esophageal, ovarian, kidney, colon, breast, and bladder cancers." (PMID 38206516, 2024). "Loss of the CDKN2A gene, encoding the tumor suppressor proteins p16INK4a and p14ARF, is a frequent event driving melanoma progression, including MM." (PMID 38191367, 2024). "The sequential loss of p16, caused by CDKN2A deletion, is considered the main reason for unregulated cell proliferation in melanoma." (PMID 39598629, 2024). "Accordingly, CDKN2A mutations are common in melanoma and even reported in 8 to 57% of familial melanoma cases." (PMID 38275910, 2024). "Dysregulation of CDKN2A is associated with various cancers, including brain tumors, melanoma and lung cancer." (PMID 38666907, 2024). "Currently available data indicate that germline CDKN2A loss of function alterations in hereditary melanoma patients mainly affect either p16INK4a alone or both p16INK4a and p14ARF, rarely affect p14ARF only 10-12." (PMID 39659584, 2024). "Since the discovery of CDKN2A, many other genetic mutations responsible for melanoma predisposition have been identified." (PMID 39335684, 2024). "These genetic alterations result from familial/inherited and somatic CDKN2A mutations to both p14ARF and p16INK4A, which impact melanoma suppression." (PMID 38275910, 2024). "Specifically, these frogs exhibited a high penetrance of spontaneous melanoma, sharing characteristics with melanomas in human hereditary melanoma caused by germline CDKN2A mutations." (PMID 39659584, 2024). "CDKN2A variant carriers face an increased risk not only for PDAC but also for melanoma and various other cancers." (PMID 38666907, 2024). "In melanoma, approximately 30% of patients have a deep deletion of the CDKN2A locus and 10%–15% have CDKN2A mutations." (PMID 38626341, 2024). "CDKN2A germline mutations remain the most critical risk factor for melanoma development and increase the risk of melanoma growth by up to 75 times under the influence of environmental risk factors such as UV exposure and sunburn." (PMID 39335684, 2024). "CDKN2A mutations are the most frequent in melanoma-prone families (20–40%) and affect the regulation of cell cycle by inhibition of CDK4." (PMID 38730639, 2024). "CDKN2A PVs give a lifetime risk of 28%–76% for melanoma and an absolute risk of 15% for pancreas cancer." (PMID 39021548, 2024). "Among the high-penetrance genes that affect melanoma risk, CDKN2A is the one that most frequently presents pathogenic variants in FM and MPM cases and, with its CDK4 binding partner, was the first gene to be identified." (PMID 39596909, 2024). "YUMM1.7 possesses several of the hallmark driver mutations in melanoma including loss of Pten and Cdkn2a and the dabrafenib sensitive BrafV600E mutation." (PMID 38421883, 2024). "Individuals with a germline CDKN2A pathogenic variant (PV) have a highly increased life time risk of melanoma and pancreatic cancer." (PMID 38822936, 2024). "Germline CDKN2A mutation is associated with an increased risk of melanoma and pancreatic cancer, and somatic CDKN2A loss is common in pancreatic cancer." (PMID 38310130, 2024). "Occurring in 1−10% of all melanoma patients, it is associated with several high‐penetrance susceptibility genes, most commonly cyclin‐dependent kinase inhibitor 2 A (CDKN2A) in 20−40% of FM cases." (PMID 39247651, 2024).